ACE (angiotensin I converting enzyme)
Diseases named in the same sentence as ACE in open-access papers (continued):
Sharing a sentence is not in itself a finding about the gene and the disease.
Stroke (continued). "However a meta-analysis of the threeplacebo-controlled trials demonstrated a significant effect of ACE inhibition onthe occurrence of all-cause mortality, cardiovascular mortality, nonfatal MI,stroke, heart failure, and coronary bypass surgery." (PMID 19390623, 2009). "ACE inhibitors or ARBs were used among 26.4% participants with CHD and 24.3% participants with stroke." (PMID 39219849, 2024). "Three of the 16 observational associations passed FDR < 0.05 in this analysis, which included ACE level on COPD, AIF1 level on HF, and SERPINF1 on stroke." (PMID 36388766, 2022). "Eight protein-disease pairs were ranked as the most valuable findings after the filtering, which include IL-7R and TNFSF12 level on asthma; ACE level on COPD; AIF1 level on HF; SERPINF1 level on stroke; and SERPINE2, F11, KLKB1, and ABO level on VTE." (PMID 36388766, 2022). "Similar drops in stroke recurrence were recorded in patients treated with perindopril, another ACE inhibitor, in the PROGRESS (perindopril PROtection aGainst REcurrent Stroke Study) study." (PMID 34201646, 2021). "Regarding clinical studies, treatment with ACE inhibitors and AT1 receptor antagonists exert preventive and therapeutic effects on stroke." (PMID 33746762, 2021). "The important biological targets for network pharmacological analysis of TM-CX and TM-JH related to stroke were PTGS2, ACE, APP, NOS1, and NOS2." (PMID 32328128, 2020). "In hypertensive outpatients with stroke, about 64% of SPs expressed a preference for ARB-based monotherapy, and only 21% for ACE-inhibitor-based monotherapy." (PMID 28515958, 2017). "An integrated package of aspirin, beta-blocker, ACE-inhibitor and statin for secondary prevention of IHD and a package of aspirin, ACE-inhibitor and statin for secondary prevention of stroke appears to be the preferred options within their categories." (PMID 27524939, 2016). "The patient was diagnosed as having a stroke with a National Institute of Health Stroke Score (NIHSS) of 3 and started on aspirin, a statin and an angiotensin converting enzyme (ACE) inhibitor." (PMID 26445807, 2015). "Angiotensin-converting enzyme (ACE) inhibitors have long been used as a treatment in primary and secondary prevention in cardiovascular disease as well as secondary stroke prevention." (PMID 22500226, 2012). "Angiotensin-converting enzyme (ACE) inhibitors can lower median CRP levels and result in better long-term outcome in stroke patients, after controlling for confounding variables and concomitant treatments." (PMID 21356305, 2011). "In addition, the low HL group had significantly lower employment and marriage rates, higher stroke and MCI comorbidity rates, lower hemoglobin levels and GNRI, lower ACE inhibitor prescription rates, and lower grip strength and FIM scores." (PMID 40728721, 2026). "In ischemic stroke, therapeutic manipulation of brain RAS has been investigated to control blood pressure and blockade of the classical RAS with ACE inhibitors and selective AT1R inhibitors (ARBs) has proven more effective than beta-blockers for secondary prevention of stroke." (PMID 35355989, 2022). "Thus, antihypertensive medications such as angiotensin-converting enzyme (ACE) inhibitors, angiotensin receptor blockers (ARBs), and calcium channel blockers (CCB) have a protective association, and there may be a beneficial effect of obtaining optimal blood pressure control after a stroke." (PMID 36338344, 2022). "The data revealed that only 48% of chronic heart disease (CHD) patients received beta blockers, 40% of CHD patients and 38% of stroke patients received ACE inhibitors, and 30% of CHD patients and 14% of stroke patients could receive statins." (PMID 33708114, 2020). "Unfortunately, Western ACE inhibitor drugs have not been tested as treatments for stroke after its occurrence." (PMID 17302964, 2006).
Stroke (continued). "Use of medications moderating hypokalemia, such as ACE inhibitors, ARBs, or MRAs, while greater in those with a prior MI or stroke compared with those without prior MI or stroke, was not different in those randomized to CTD compared with HCTZ over the course of the study." (PMID 38743423, 2024). "Those in the group with prior MI or stroke had similar use of an ACE inhibitor or ARB at year 2 compared with those without MI or stroke (51.5% vs 48.9%; P = .12) but were more likely to be using an SGLT2 inhibitor at 2 years (7.5% vs 3.9%; P < .001) (eTable 2 in Supplement 2)." (PMID 38743423, 2024). "In addition to the association between ACE polymorphism and IS, the contribution of other risk factors, such as the relation between ACE gene I/D polymorphism and patients with HTN without known histories of stroke, was studied in different populations." (PMID 37034069, 2023). "Univariable Cox regression analysis revealed that age, history of a malignancy or stroke, not using an ACE-inhibitor/angiotensin-II (AT2) antagonist or aspirin, an impaired LVEF, an MR grade ≥2 and multivessel disease during pPCI were significant predictors for 5‐year all-cause mortality." (PMID 31392625, 2019). "Use of an ACE-inhibitor was associated with unadjusted HR of 1.05 (0.58–1.89), p = .88, and use of ARB was associated with unadjusted HR of 1.36 (0.73–2.54), p = .33 for incident strokes and were therefore not included in final adjusted models." (PMID 30471633, 2019). "A package consisting of aspirin, beta-blocker ACE-inhibitor and statin for secondary prevention of IHD costs US$1850 per DALY averted, while a package consisting of aspirin, ACE-inhibitor and statins for secondary prevention of stroke costs US$1060 per DALY averted." (PMID 27524939, 2016). "We evaluate cost-effectiveness of statins, diuretics, ACE inhibitors, calcium channel blockers and beta-blockers, for Australian men and women, aged 35 to 84 years, who have never experienced a heart disease or stroke event." (PMID 22657090, 2012). "However, this inference was indirect, as the patients in these studies were already taking ACE Inhibitors at the onset of acute stroke and were not put on these drugs after the onset of the stroke." (PMID 21085523, 2010). "Notably, our research revealed that continuing ACE inhibitors neither exhibited a significant association with postoperative AKI or postoperative cardiac events, such as vasopressor use, postoperative atrial fibrillation, or stroke nor did they impact the length of hospital stays." (PMID 38783960, 2024). "The current evidence is primarily derived from trials studying ACE inhibitors or diuretics, although no definite conclusions can be drawn regarding an optimal SBP target after stroke or TIA." (PMID 33430236, 2021). "Additionally, 75% of patients with recurrent stroke had a combined APOE ε2ε3 and ACE I/D genotype, whereas in the pediatric group without recurrent stroke, it was only 6%." (PMID 31906461, 2020).
angioedema (300 papers, 2006 to 2026). Swelling involving the deep dermis, subcutaneous, or submucosal tissues, representing localized edema. "Bradykinin-mediated angioedema, typically associated with ACE inhibitors, usually has a slower onset and is less likely in this context." (PMID 40599632, 2025). "Taken together, the clinical context, lack of allergic, hereditary, or acquired features, temporal association with ACE inhibitor therapy, and resolution after targeted therapy and drug withdrawal all support a diagnosis of ACE inhibitor-induced angioedema." (PMID 41035577, 2025). "In summary, this case highlights the importance of early recognition and aggressive management of ACEi-induced angioedema and underscores the potential of ACE inhibitors to cause life-threatening complications." (PMID 40365500, 2025). "First, the ARBs exert a feedback rise in plasma levels of angiotensin II by suppressing the Angiotensin II type 1 (AT 1) receptor, and this causes self-inhibition of the ACE, causing BK accumulation and angioedema." (PMID 41440559, 2025). "While neprilysin alone brought no significant benefit, combined with ACEi it caused harm due to the drug inhibiting both ACE and neprilysin, causing a build-up of bradykinin and angioedema." (PMID 39776087, 2025). "This is consistent with previous literature, where ARB-induced angioedema was noted to occur in approximately 0.11% of patients, much less frequently than with ACE inhibitors, yet still poses a significant risk in susceptible individuals." (PMID 40636633, 2025). "Given the history of recurrent episodes of angioedema, the absence of laboratory findings suggestive of hereditary angioedema, and the temporal association with ACE inhibitor use, the clinical diagnosis of perindopril-induced angioedema was made." (PMID 40365500, 2025). "Drug-induced angioedema is frequently associated with angiotensin-converting enzyme (ACE) inhibitors, whereas calcium channel blockers (CCBs) like amlodipine are rarely implicated." (PMID 40786263, 2025). "ACE inhibitors can also cause angioedema, which can be life-threatening and is a reason to discontinue ACE inhibitors forever." (PMID 39100000, 2024). "ACE inhibitors are a medication class that is associated with angioedema in 0.1-0.7% of treated patients." (PMID 38910667, 2024). "The occurrence of angioedema in individuals initiating ACE inhibitor treatment varies, influenced by various risk factors, including both genetic and environmental exposures." (PMID 38543146, 2024). "One case of total plasma prekallikrein deficiency has had angioedema due to an ACE inhibitor emphasizing the contribution of tissue kallikrein to the level of bradykinin in plasma, or perhaps within the interstitium." (PMID 38332896, 2024). "If elevated bradykinin levels are the primary reason behind angioedema owing to ACE inhibitor use, ARBs are thought to cause very few, if any, occurrences of the condition." (PMID 39524712, 2024). "Such polymorphisms can reduce enzyme activity, increasing susceptibility to ACE inhibitor-induced angioedema." (PMID 38543146, 2024). "It is worth noting that diabetes mellitus is associated with a reduced risk of ACE inhibitor-induced angioedema." (PMID 38543146, 2024). "Angiotensin converting enzyme (ACE) inhibitor-associated angioedema is the most common cause of angioedema seen in the emergency department (ED) and can be associated with a high morbidity." (PMID 38546304, 2024). "In recognition of the elevated risk of angioedema associated with the concomitant administration of ACE inhibitors and mTOR-Is, including sirolimus and everolimus, the FDA issued a warning, underlining the critical importance of these findings." (PMID 38205154, 2024). "The clinical manifestations of ACE inhibitor-induced angioedema are associated with elevated levels of bradykinin." (PMID 38543146, 2024).
angioedema (continued). "The only published case reports of angioedema after TNK administration occurred in a patients who were currently using an ACE inhibitor, which is a known risk factor for development of angioedema." (PMID 39158246, 2024). "The fact that traditional ACE inhibitors are linked with side effects such as dry cough and angioedema, despite the fact that they are clinically successful, highlights the continuous need for alternatives that are both safer and more effective." (PMID 39452857, 2024). "Since ACE inhibitors increase the risk of angioedema in black patients, ARBs are a better option for this group of people." (PMID 39493194, 2024). "Triple therapy involving an ACE inhibitor, a dipeptidyl peptidase-IV inhibitor, and a calcium channel blocker is reported to be associated with angioedema." (PMID 39124556, 2024). "Deficiencies in these secondary enzymes are capable of predisposing patients to bradykinin-associated angioedema development when started on an ACE inhibitor." (PMID 38957198, 2023). "As conventional ACE inhibitors, such as captopril, are not domain-selective and thus induce a higher risk of developing BK-mediated angioedema, this property of C-domain selectivity of BPPs makes them more beneficial than ACE inhibitors such as captopril." (PMID 37892221, 2023). "Several previous studies reported that ACE inhibitors, such as lisinopril, were related to an increased risk of angioedema mainly due to inhibition of the angiotensin-converting enzyme and subsequent blockade of bradykinin degradation." (PMID 38045916, 2023). "Healthcare providers ought to be mindful of the increased risk of angioedema when prescribing dipeptidyl peptidase-IV inhibitors and calcium-channel blockers with ACE inhibitors, as these are frequently used medications." (PMID 37908932, 2023). "For angioedema, the substantial relative risk increase with ACE inhibitors only translated in a small risk increase on the absolute scale due to the limited baseline angioedema risk." (PMID 36991144, 2023). "Angioedema is a rare but potentially life-threatening complication associated with angiotensin-converting enzyme (ACE) inhibitors." (PMID 37908932, 2023). "Currently, there is conflicting information on the medical management of ACE inhibitor-associated angioedema." (PMID 38957198, 2023). "While ARNIs are effective, they are more frequently associated with symptomatic hypotension and increased angioedema incidence than an ACE inhibitor such as enalapril." (PMID 38161537, 2023). "Among them, we identified thirteen (15%) ACE inhibitor-induced, one unspecified infection-associated, one Helicobacter Pylori-related, three (3,7%) food-related, and three (3,7%) drug- related angioedema patients." (PMID 38124188, 2023). "One study observing the management of ACE inhibitor-associated edema in the ED setting noted that 41% of patients with this subtype of angioedema required admission for inpatient care." (PMID 38957198, 2023). "Given that all drugs in this class potentially have a high risk of angioedema, the enthusiasm to further study the combination of neprilysin inhibitors and ACE inhibitors has dissipated." (PMID 36777165, 2023). "Though ACE inhibitor-associated angioedema will appear similar to HAE with bradykinin overactivation, obtaining serum levels of C1 inhibitor and C4 will assist in the diagnosis." (PMID 38957198, 2023). "The mechanism for the increased risk in angioedema is likely attributable to an increase in circulating bradykinins caused by inhibition of both ACE and neprilysin." (PMID 36777165, 2023). "This becomes evident when evaluating the safety of thiazide or thiazide-like diuretics on angioedema and cough, both adverse events linked to treatment with ACE inhibitors." (PMID 36991144, 2023).
angioedema (continued). "On the other hand, the inhibition of the ACE also causes the production of bradykinin and substance P. Therefore, angioedema and dry cough were observed as side effects among patients undergoing ACE-inhibitor treatment." (PMID 35214118, 2022). "Dipeptidyl peptidase-4 (DPP-4) plays a minor role in degrading vasoactive peptides that cause angioedema when angiotensin-converting enzyme (ACE) is present and fully functional." (PMID 35907939, 2022). "A prospective study demonstrated that ACE inhibitors increase the risk of developing angioedema in blacks by threefold compared with whites." (PMID 36430371, 2022). "The drug is tolerated well and linked to a low incidence of angioedema due to a smaller increase in bradykinin in patients as compared with ACE inhibitors such as enalapril." (PMID 36003518, 2022). "Angioedema is mediated by bradykinin (HAE, acquired C1-inhibitor deficiency, and ACE inhibitor-associated angioedema)." (PMID 36381703, 2022). "Angiotensin converting enzyme inhibitors (ACE-Is) have long been associated with angioedema and cough." (PMID 35573493, 2022). "Since the mechanism behind angioedema is primarily a result of increased bradykinin levels, ACE inhibitors are the drugs associated with this side effect, not ARBs." (PMID 36430371, 2022). "A factor that we must highlight is the reported increased risk of ACE inhibitor angioedema within Black people that is described in the NICE guidance evidence reviews." (PMID 34508156, 2022). "The most common causes of angioedema include hereditary or acquired deficiency of C1-esterase inhibitor and medications, such as angiotensin-converting enzyme (ACE) inhibitors." (PMID 36057741, 2022). "Angiotensin converting enzyme (ACE) inhibitor-associated angioedema (ACEi-AE): ACE is a protease that cleaves BK." (PMID 33534062, 2021). "Subjects taking ACE inhibitors had an adjusted three-fold increased risk of urticaria/angioedema (RR 2.98, 95% CI: 1.12–7.96)." (PMID 34579248, 2021). "It is worth it to mention that SAC treatment in combination with ACE inhibition was associated with high rates of angioedema, resulting from increased bradykinin, a substrate of both neprilysin and ACE." (PMID 35197849, 2021). "The suppression of RAAS while enhancing the NP system via the simultaneous inhibition of both angiotensin converting enzyme (ACE) and neprilysin has been proven less successful and has the risk of angioedema." (PMID 34443591, 2021). "As ACE plays a pivotal role in degrading bradykinin, ACE inhibitors (ACEi) have been implicated in angioedema, mainly for causing uncontrollable bradykinin generation." (PMID 34354123, 2021). "Patients on angiotensin-converting enzyme (ACE) inhibitor are at a higher risk for angioedema, which when involves oropharynx can compromise airway." (PMID 33732203, 2021). "In such patients, it has been suggested that marked obesity, resulting in airway narrowing, is a risk factor for upper airway obstruction secondary to ACE inhibitor-induced angioedema." (PMID 33398469, 2021). "In particular, it was found that DPP-IV inhibitors increased the risk of angioedema in patients concurrently treated with angiotensin-converting enzyme (ACE) inhibitors (ACEIs), a class of medications extensively used in clinical practice." (PMID 34872575, 2021). "Omapatrilat, a dual NEP inhibitor–ACE inhibitor, was a promising antihypertensive drug but failed in trials due to angioedema, an effect possibly caused by inhibition of both the N- and C-domains of ACE." (PMID 34304582, 2021). "This favors that among the risk factors that predispose individuals to develop angioedema, ACE inhibitor-associated cough is a major one." (PMID 34917435, 2021). "Individuals with other forms of angioedema such as acquired angioedema, ACE-inhibitor associated angioedema or hereditary angioedema with normal C1 inhibitor were excluded." (PMID 34627363, 2021).